PARP1 (poly(ADP-ribose) polymerase 1)
Diseases named in the same sentence as PARP1 in open-access papers (continued):
Sharing a sentence is not in itself a finding about the gene and the disease.
glioblastoma (continued). "Preclinical studies have demonstrated that PARP-1 targeting alpha therapy ([211At]MM4) is beneficial in neuroblastoma and augments PD-1 immune checkpoint blockade in the glioblastoma." (PMID 36834491, 2023). "In this study, we found that histone deacetylase inhibits valproic acid (VPA), synergized with PARP1 inhibitor (PARPi), talazoparib (BMN-673), and alkylating agent, and temozolomide (TMZ) to induce DNA damage and reduce glioblastoma multiforme." (PMID 37763083, 2023). "In the first part of our study, we investigated the response of patient-derived glioblastoma cells and normal astrocytes to the VPA inhibitor, both as a single agent and in combination with an alkylating agent and PARP1 inhibitor." (PMID 37763083, 2023). "In addition, high PARP1 expression was positively associated with microsatellite instability event in COAD, KIRP, BRCA, glioblastoma multiforme (GBM), lung squamous cell carcinoma (LUSC), LGG, READ, UCEC, SKCM and LUAD (P < 0.05)." (PMID 34531868, 2021). "Depletion of VRK1, an enzyme that regulates chromatin dynamic reorganization and facilitates resistance to DNA damage, was performed in glioblastoma cells treated with temozolomide, an alkylating agent used for GBM treatment; and olaparib, an inhibitor of PARP-1, used as sensitizer." (PMID 34195200, 2021). "We recently published work showing that, after the inhibition of PARP-1, an enhancement of the CLytA-DAAO effect can be observed in glioblastoma cell lines." (PMID 33198289, 2020). "In glioblastoma, the research suggested that miR-708 affects glioblastoma cell proliferation, invasion, and apoptosis through regulating AKt1, CCND1, MMP2, EZH2, Parp-1 and Bcl219." (PMID 33028966, 2020). "The current study investigates the trimodal combination of ABT-888, a potent inhibitor of PARP1-2, ionizing radiation and temozolomide(TMZ)-based chemotherapy in glioblastoma (GBM) cells." (PMID 23510353, 2013). "Besides, brain or spinal cord tumors remain difficult types of cancers to treat, such as glioblastoma (GBM), even after four PARP inhibitors were approved by FDA as PARP1 overexpression is present in various cancers." (PMID 36438061, 2022). "PARP-1 protein is usually not present in normal neurons, but human primary glioblastoma tissues showed positive immunohistochemical staining for PARP-1." (PMID 28346397, 2017). "Surprisingly, in the same CRISPR-based screens that revealed the critical role of the FA genes in TMZ/MNNG resistance, PARP1 depletion did not hyper-sensitize MGMT-negative glioblastomas to TMZ and led to only a minor increase in MNNG sensitivity in RPE1 cells." (PMID 39011394, 2024). "In human U251 glioblastoma (GBM) and HEK-293 cells, KAT2A depletion expectedly decreased the level of Ksuc in specific gene promoter sites; SIRT7 is recruited to DNA DSBs dependent on poly(ADP-ribose) polymerase 1 (PARP1), thereby promoting DSB repair and chromatin condensation." (PMID 38315203, 2024). "A novel radioactive binding assay using [3H]WC-DZ in a PARP-1 high expression glioblastoma cell line was validated and set up for in vitro measurement of PARP-1 in cancer tissues or cell lines and for high throughput screening of next-generation PARP-1 inhibitors." (PMID 34069967, 2021). "To assess cellular toxicity to a single or combined treatment of PARP1 inhibitor (Olaparib; 10nM, 1μM and 10μM) and/or ATR inhibitor (AZD6738; 0.5μM; 1μM, 10μM and 20μM), we performed clonogenic survival assays using two different glioblastoma cell lines (LN428 and LN18)." (PMID 29348879, 2017). "Similarly, Karlovic and colleagues (2007) found that LiCl treatments (20 mmol/L) in A1235 glioblastoma cells altered the levels of proteins such as Bcl-2 and proCAS-3, and there was no cleavage of PARP1, reinforcing with our work that lithium does not affect this pathway." (PMID 39339471, 2024).
glioblastoma (continued). "One bioinformatic analysis showed that it could be used as a biomarker in glioblastoma progression, while another study revealed that TRAF3IP2-AS1 propelled the development of a specific type of renal cancer (NONO-TFE3 translocation type) via PTEN downregulation and PARP1 m6A stimulation." (PMID 36992083, 2023).
diabetes (78 papers, 2009 to 2025). "Another study linked high glucose and PARP1/ARTD1 levels in streptozocin-induced diabetes mellitus in apolipoprotein E-deficient mice." (PMID 37513811, 2023). "PARP1 and PARylation homeostasis have also been implicated in multiple diseases, including inflammation, stroke, diabetes and cancer." (PMID 36077699, 2022). "The elevated expression of cleaved PARP-1 caused by diabetes was decreased following nicotinamide application." (PMID 35334819, 2022). "The inhibition or deficiency of PARP1 is protective in models of the cell and rat/mouse injury paradigms, including retinal degeneration diseases, stroke, diabetes, I/R injury, neurodegenerative disease, and heart failure." (PMID 35806303, 2022). "Hyperactivation of PARP1 is associated with impaired DNA methylation processes in peripheral blood mononuclear cells from type 2 diabetes mellitus patients." (PMID 36077699, 2022). "The overexpression of the PARP1 gene is associated with tissue damage and destruction of β cells, being a highly relevant factor in endothelial dysfunction in diabetes." (PMID 34366888, 2021). "An increase in PARP1 activity in the failing heart was linked to coronary artery disease in diabetes patients." (PMID 34479416, 2021). "This activation by ONOO− of the PARP-1 axis plays an important role in myocardial ischemia, diabetes and diabetes associated with cardiovascular dysfunction." (PMID 32486343, 2020). "Poly(ADP-Ribose) Polymerase-1 (PARP-1) deficient mice are protected from STZ induced diabetes, suggesting this pathway is essentially involved in neurodegeneration caused by this molecule." (PMID 32303185, 2020). "Hyperglycemia associated with diabetes mellitus is known to impair endothelial function, as manifested by PARP1 activation and resulting oxidative and inflammatory stresses." (PMID 26986624, 2016). "With regard to diabetes, PARP-1 deficiency provides protection from experimentally induced diabetes." (PMID 23555743, 2013). "Adoptive transplantation of leukocytes (bone-marrow) deficient in iNOS or PARP1 was sufficient to inhibit diabetes-induced retinal capillary degeneration in WT animals." (PMID 24205223, 2013). "Other investigators have linked PARP1 hyperactivity to degenerative diseases such as diabetes, 1-methyl-4-phenyl-1,2,3,6-tetrahydropyridine (MPTP)-induced parkinsonism and injury induced brain disorders." (PMID 22848760, 2012). "PARP1 is also frequently implicated in inflammatory disorders such as sepsis, diabetes, myocardial infarction and stroke, as considerable by-stander DNA damage resulting from the generation of reactive oxygen species hyperactivates PARP1." (PMID 24970148, 2012). "Notably, in a diabetic rat model, PARP-1 was associated with high mobility group box 1, an inflammatory factor that up-regulates diabetes-induced retinal cell apoptosis markers." (PMID 39458649, 2024). "We aimed at investigating whether alteration of miR-194-dependent MMPs and PARP-1 causes renal fibrosis in diabetes kidney, and whether H2S ameliorates fibrosis." (PMID 28883608, 2017). "Different works have reported that both the pharmacological inhibition of PARP and a deficiency of PARP-1 have a protective role in inflammatory diseases, such as LPS-induced septic shock, uveitis, colitis, streptozotocin-induced diabetes, asthma-related lung inflammation, and atherosclerosis." (PMID 26339143, 2015). "It was previously demonstrated that PARP-1 deficient mice are protected against several pathological conditions such as myocardial infarction, streptozotocin-induced diabetes, LPS-induced septic shock, collagen-induced arthritis etc., suggesting that PARP-1 is implicated in inflammatory disorders." (PMID 26252217, 2015). "Furthermore, diabetes-induced retinal capillary loss was also inhibited in animals deficient in leukocyte and inflammation associated proteins such as iNOS or PARP1." (PMID 24205223, 2013).
diabetes (continued). "Several studies have shown that pharmacological inhibition or gene deletion of PARP-1 could prevent tissue damage induced by oxidative stress associated with several diseases like stroke, diabetes, myocardial ischemia-reperfusion and Parkinson's disease." (PMID 24086258, 2013). "Research shows that PARP1 knockout (KO) mice exhibit resistance to diabetes, and inhibiting PARP1, particularly with PJ34, alleviates complications in type 2 diabetes patients." (PMID 39057094, 2024). "This implies distinct mechanisms at play in diabetes or high-glucose states, differing from PARP-1 activation mechanisms during oxygen and nitrogen stress." (PMID 39458649, 2024). "Real-time PCR results showed that there was a significantly higher level of PARP1 mRNA expression in the diabetes group’s hippocampus as compared to the control group (p < 0.0001)." (PMID 38129872, 2023). "Upregulation of poly(ADP-ribose) polymerase-1 (PARP-1), a regulator of transcription factor binding on a gene promoter, in diabetes, is implicated in the increased binding of NF-kB at MMP-9 promoter, increasing its transcription." (PMID 36672234, 2023). "It has been demonstrated that PARP1 plays an important role in the pathogenesis of endothelial dysfunction in diabetes." (PMID 36829935, 2023). "The proportion of PARP-1-positive cells was increased in the diabetes group compared to the normal control group at 4 weeks and 12 weeks after induction of diabetes (Both p < 0.001)." (PMID 35334819, 2022). "Elevated cleaved PARP-1 expression was suppressed by nicotinamide treatment at 12 weeks after induction of diabetes (p < 0.001)." (PMID 35334819, 2022). "In Western blot analysis, the increased expression of cleaved PARP-1 in diabetes was attenuated by nicotinamide treatment at 12 weeks after induction of diabetes." (PMID 35334819, 2022). "Despite these beneficial effects, the use of PARP1 modulating agents in diabetes treatment is largely neglected, primarily due to the poorly studied mechanistic action of PARP1 catalytic function in human β cell development." (PMID 36513699, 2022). "Overactivation of the DDR and PARP1 signaling pathways has also been demonstrated in other ectopic calcification disorders such as diabetes mellitus and CKD, suggesting that it is a universal and common disease mechanism in aberrant tissue mineralization." (PMID 35163765, 2022). "PARP1 knockout (KO) mice are resistant to diabetes, while PARP1 overactivation contributes to β cell death." (PMID 36513699, 2022). "The upregulated expression of PARP-1 by diabetes was attenuated by nicotinamide treatment at 12 weeks after induction of diabetes (p < 0.001)." (PMID 35334819, 2022). "The expression of PARP-1, measured by immunofluorescence staining, was increased in the diabetes group, and nicotinamide treatment alleviated PARP-1 immunofluorescence." (PMID 35334819, 2022). "A few genes/proteins are considered biomarkers of parthanatos; for example, PARP1 is a therapeutic target in the stroke, trauma, I/R injury, and diabetes model." (PMID 35806303, 2022). "Inhibition of the DDR by treatment with PARP1 inhibitors such as minocycline was shown to significantly ameliorate the ectopic calcification phenotype in experimental models of diabetes mellitus and CKD." (PMID 35163765, 2022). "An elevated expression of cleaved PARP-1 was attenuated by nicotinamide treatment at 12 weeks after the onset of diabetes (p < 0.001)." (PMID 35334819, 2022). "PARP1@PLS‐PT100 nanospheres mitigate diabetes‐induced dysregulation in cells, thereby attenuating senescence and restoring tissue repair." (PMID 34738744, 2022). "On the other hand, PARP-1 inhibition has also been proven capable of ameliorating neuropathy in diabetes." (PMID 34943979, 2021). "In a diabetes model simulated by incubating with fetal bovine serum in Schwann cells, calcitriol treatment can reduce cell apoptosis and reduce cleavage of PARP1." (PMID 34393753, 2021).
diabetes (continued). "Diabetic rats fed with minocycline daily for 8 weeks exhibited decreased apoptosis of retinal cells through inhibition of PARP-1, which was abnormally activated by diabetes-induced DNA damages." (PMID 33931128, 2021). "We proposed working schematic of PARP-1 depletion-mediated attenuation of atherosclerotic calcification in diabetes." (PMID 31924749, 2020). "We found that PARP-1 deletion attenuated atherosclerotic calcification, reduced the content of aortic calcium, and decreased vessel stiffening in diabetes." (PMID 31924749, 2020). "The physio-pathological role of PARP-1 hyper-activation through DNA damage is well exemplified by using PARP-1 inhibitors in the experimental model of diabetes, inflammation and cancer." (PMID 33158052, 2020). "Our results demonstrate the key role of macrophage-specific PARP-1 in the development of arteriosclerotic calcification in diabetes." (PMID 31924749, 2020). "In fact, Parp‐1 knockout mice are resistant to ischaemic stroke, as well as to LPS‐induced septic shock, and to streptozotocin‐induced diabetes." (PMID 30804002, 2019). "Male C57BL/6 mice or PARP-1−/− mice were treated with streptozotocin (STZ) by intraperitoneal injection for 5 consecutive days to induce diabetes." (PMID 27027354, 2016). "Previous study has demonstrated that PARP-1 can be activated byin STZ-induced diabetes and plays a critical role in the development of myocardial and endothelial cardiovascular dysfunction in diabetes rats and mice." (PMID 27027354, 2016). "PARP1 deficiency in mice and PARP inhibitors protect against stroke, I/R injury, sepsis, diabetes, and pancreatitis, suggesting that PARP1 is a potential target in inflammatory disease." (PMID 25904867, 2015). "YY1 participates in the regulation of Parp-1, the chemokine receptor Cxcr4 and the antiinflamatory cytokine IL-4 that protects against diabetes development." (PMID 23555743, 2013). "Constant apocynin intake from the onset of diabetes significantly attenuated diabetes-induced upregulation of PARP-1/2." (PMID 24347828, 2013). "Namely, PARP-1 knockout (PARP−/−) mice were shown to be resistant to streptozotocin (STZ) -induced diabetes, restoring normal blood glucose and pancreatic islet structure." (PMID 23555743, 2013). "Extensive PARP-1 activation by DNA damage contributes to the development and progression of various chronic diseases including diabetes, cancer, viral infections and neurodegenerative diseases." (PMID 24086258, 2013). "Moreover, YTHDF2 epigenetically suppressed m6A modification of PARP1 and regulated diabetes-induced PARP1 expression in DR." (PMID 41585810, 2025). "However, in diabetes, elevated glucose levels upregulate PARP-1 expression, exacerbating vascular complications and inflammation." (PMID 40072104, 2025). "Indeed, ADP-ribosylation has a role in β-cell death; in murine islets, PARP1 induces cytokine-mediated β-cell death, and its deletion protects against streptozotocin-mediated diabetes." (PMID 38383396, 2024). "In addition, let-7a-5p’s recognized target genes, p66Shc, CASP3, and PARP1, were elevated in diabetes circumstances whereas let-7a-5p was downregulated." (PMID 38129872, 2023). "At 4 and 12 weeks after induction of diabetes, PARP-1 immunostaining was found mostly in the GCL." (PMID 35334819, 2022). "PARP1 overexpression was also shown to be involved in heart failure.It had been reported that heart dysfunction was associated with an increase in poly (ADP-ribosyl)ation in mouse and rat models of diabetes." (PMID 35178387, 2022). "Additionally, PARP1 inhibition (PARPi) improves diabetes complications in patients with type-2 diabetes." (PMID 36513699, 2022). "However, cleaved PARP-1 expression was increased in the diabetes group compared to the normal control group at 4 and 12 weeks after induction of diabetes (p = 0.002, p < 0.001, respectively)." (PMID 35334819, 2022).
diabetes (continued). "BBR may have a protective effect on diabetes by increasing the expression of PARP-1 protein, increasing islet β-cell proliferation and antioxidant enzyme activity and reducing lipid peroxidation." (PMID 34630099, 2021). "In addition, PARP-1 inhibition downregulates Stat1/Runx2 transcriptional activity and alleviates atherosclerotic calcification in diabetes." (PMID 31924749, 2020). "We therefore speculated that PARP-1 could modulate osteogenic differentiation and thus contribute to atherosclerotic calcification in diabetes." (PMID 31924749, 2020). "Poly [ADP-ribose] polymerase 1 (PARP-1) deficiency can reduce the expression of Runx2 by inactivating STAT1 and also accelerate the pace of M1 polarization into M2, which prevents the progression of diabetes-induced atherosclerotic calcification." (PMID 32457633, 2020). "Boswellia triterpenoids targeted the cancer-relevant proteins (poly(ADP-ribose) polymerase-1, tankyrase, and folate receptor β), inflammation-relevant proteins (phospholipase A2, epoxide hydrolase, and fibroblast collagenase), and the diabetes target 11β-hydroxysteroid dehydrogenase." (PMID 30200355, 2018). "Therefore, the BC-mediated insulin sensitivity is partly owed to the increased Nrf2 and the decreased PARP-1 to alleviate diabetes-induced oxidative stress and inflammation." (PMID 30072896, 2018). "Thus, the findings from our study suggest that GYY alleviates kidney remodeling by modulating PARP-1 in part through regulation of metabolic pathway involved in diabetes." (PMID 28883608, 2017). "Indeed, in a streptozotocin-induced diabetes model, pancreatic beta-cell death was mediated by Parp-1 activation and by Mpg-initiated BER, molecular events known to contribute to tissue damage by depleting cells of free energy." (PMID 28903334, 2017). "Thus, the PARP1 activation should be considered in the development of effective statin therapies for diabetes." (PMID 28004006, 2016). "A more recent study in diabetic rats suggests that minocycline may act at least in part by attenuating the diabetes-mediated upregulation of poly [ADP-ribose] polymerase 1 (PARP-1), an enzyme involved in DNA repair." (PMID 27618014, 2016). "Therefore, our findings suggest that targeting autophagy or PARP1-AMPK-mTOR pathways should be considered in the development of effective statin therapies for diabetes." (PMID 28004006, 2016). "Diabetes-induced inflammatory changes, superoxide production, and degeneration of retinal capillaries are inhibited in diabetic mice in which inflammatory proteins (iNOS and PARP-1) are deleted from BM cells." (PMID 26245868, 2015). "PARP1 is heavily automodified upon bacterial infection and Parp1−/− mice have proven to be resistant to inflammation in different experimental models, such as LPS-induced septic shock and streptozotocin-induced diabetes." (PMID 24243533, 2014). "This is a PARP-1-dependent ubiquitarious form of cell death involved in all tissues of the organism and in pathologies as diverse as Parkinson's disease, stroke, heart attack, diabetes, and ischemia." (PMID 20003343, 2009). "Several FDA-approved PARP1 inhibitors, initially proposed for use in tumor treatment, have also demonstrated therapeutic effects in models of non-cancerous diseases such as stroke, Parkinson’s disease, Alzheimer’s disease, multiple sclerosis, diabetes, and myocardial infarction." (PMID 39595575, 2024). "RSV can probably be useful as an inhibitor of unwanted PARP1 hyper-activation in the prevention and/or in the treatment of some metabolic and inflammatory diseases such as cardiovascular, Parkinson’s, and Alzheimer’s diseases, neurodegenerative disorders, and diabetes." (PMID 39595575, 2024). "Collectively, these results indicate that PARP-1 depletion inhibited the osteogenic and atherogenic phenotype of macrophages by targeting Stat1 and may subsequently decrease atherosclerotic calcification in diabetes." (PMID 31924749, 2020).